EDNRB (endothelin receptor type B)
Diseases named in the same sentence as EDNRB in open-access papers (continued):
Sharing a sentence is not in itself a finding about the gene and the disease.
Cognitive impairment (3 papers, 2018 to 2024). Abnormal cognition is characterized by deficits in thinking, reasoning, or remembering. "In transgenic mice, the over-expression of ET-1 by CECs is a critical factor in astrogliosis and relates to the severity of cognitive impairment,; the potential mechanism is c-Jun expression activated by JNK and p38MAPK after ET-1 binding to the endothelin receptor type B (ETB) in astrocytes." (PMID 30505270, 2018).
diabetes (3 papers, 2008 to 2024). "It is worth mentioning that all of these genes have been reported to be associated with the progression of diabetes, while EDNRB has been reported to be associated with the onset and progression of COPD, demonstrating the reliability of the analytical method." (PMID 39845878, 2024). "In this study, we identified EDNRB as a shared biomarker for diabetes and COPD, and accurately predicted the diagnosis of diabetes and COPD." (PMID 39845878, 2024). "While the EDN1 (endothelin 1) alterations have been well described in DR, induction of EDN2 (endothelin 2), a potent vasoconstrictor, and the endothelin receptor EDNRB (endothelin receptor B) have been described after 6 months of diabetes and light injury." (PMID 18554398, 2008). "Recently, the role of EDNRB in diabetes and COPD has become a research focus." (PMID 39845878, 2024). "Beyond confirming the involvement of EDNRB and TMEM27 in diabetes or COPD, our study reveals their interactions with immune cell infiltration and metabolic pathways in both diseases." (PMID 39845878, 2024). "Multiple machine learning algorithms identified 4 shared biomarkers for COPD and diabetes, including CADPS, EDNRB, THBS4 and TMEM27." (PMID 39845878, 2024). "While prior studies have explored the role of EDNRB and TMEM27 in either diabetes or COPD, our study is among the first to leverage multi-omics data to identify these biomarkers as shared regulatory nodes between the two diseases." (PMID 39845878, 2024). "Ultimately, we conducted a cross-analysis of the 4 potential biomarkers gene sets and 4 genes as shared biomarkers for COPD and diabetes, including CADPS, EDNRB, THBS4 and TMEM27." (PMID 39845878, 2024). "While this study provides compelling evidence for the role of CADPS, EDNRB, THBS4, and TMEM27 as shared biomarkers between COPD and diabetes, it is important to acknowledge that the specific molecular mechanisms underlying their involvement in disease progression remain incompletely understood." (PMID 39845878, 2024). "In this study, we integrated microarray data from multiple cohorts of COPD and diabetes patients, and comprehensively utilized various machine learning algorithms to identify shared biomarkers in COPD and diabetes patients, including CADPS, EDNRB, THBS4 and TMEM27." (PMID 39845878, 2024).
diabetic nephropathy (3 papers, 2019 to 2025). "While atrasentan reduced proteinuria by 34% in diabetic nephropathy trials, its oncology applications are limited by fluid retention, potentially linked to EDNRB’s ceRNA regulatory network involving lncRNA FENDRR and miR-148a." (PMID 40589973, 2025).
ischemic stroke (3 papers, 2014 to 2018). A stroke disorder caused by obstruction of blood flow to the brain, due to thrombotic (local blood clot formation) or embolic (due to a blood clot or other material traveling from another site) event. "There are several works that concern the investigation of the effect of EDN1, EDNRA, and EDNRB genetic polymorphisms on ischemic stroke (IS) development." (PMID 29849817, 2018). "Finally, increased expression of the vasoconstrictor receptor EDNRB is associated with vasoconstriction of cerebral arteries in rodent models of ischemic stroke." (PMID 27809765, 2016).
lung adenocarcinoma (3 papers, 2021 to 2025). A carcinoma that arises from the lung and is characterized by the presence of malignant glandular epithelial cells. "For the second intersected biomarker identified here (PAL of Endothelins main pathway), the association of endothelin receptor type B with the response of lung adenocarcinomas to immunotherapy was recently reported." (PMID 39723204, 2024). "Our expression analysis revealed that CDH3, EDNRB, MAOA, and PLA2G1B matched our differential gene analysis results in IPF, Lung Adenocarcinoma (LUAD), and Lung Squamous Cell Carcinoma (LUSC) tissues." (PMID 40589973, 2025). "Our bioinformatic analysis identified six downregulated DEGs (EDNRB, RXFP1, P2RY1, CALCRL, TEK, and ANGPT1) between lung adenocarcinoma and normal lung tissues based on two different microarray datasets." (PMID 34039311, 2021).
oral cancer (3 papers, 2013 to 2020). "Viral- and nonviral-mediated delivery of genes for the μ-opioid receptor and the endothelin B receptor (OPRM1 and EDNRB, respectively) produce endogenous analgesia through the secretion of opioids by the carcinoma in preclinical oral cancer pain models." (PMID 30405367, 2018).
renal cell carcinoma (3 papers, 2013 to 2020). "An increase in endothelin receptor type B, phospho-S6 and CD44 expression and more frequent overexpression in metastases than in corresponding primary renal cell cancers were shown." (PMID 32668608, 2020).
small cell lung carcinoma (3 papers, 2002 to 2020). Small cell lung cancer (SCLC) is a highly aggressive malignant neoplasm, accounting for 10-15% of lung cancer cases, characterized byrapid growth, and early metastasis. "A study showed that EDNRB expression is reduced in large primary UM and small cell lung cancer with high metastatic genotype and phenotype." (PMID 33196683, 2020).
chronic obstructive pulmonary disease (2 papers, 2018 to 2021). A chronic and progressive lung disorder characterized by the loss of elasticity of the bronchial tree and the air sacs, destruction of the air sacs wall, thickening of the bronchial wall, and mucous accumulation in the bronchial tree. "Recently, it was reported that EDNRB expression was significantly increased in chronic obstructive pulmonary disease (COPD) patients and was effectively reduced after celastrol treatment, which supposes an inflammation-related role of EDNRB in COPD." (PMID 34039311, 2021).
Colon Cancer (2 papers, 2020 to 2025). "EDNRB is considered as the predominant receptor in normal colon, but in colon cancer it is down-regulated in cancer associated blood vessels, fibroblasts, and epithelial cells." (PMID 32194414, 2020). "In colon cancer, EDNRA expression is more dominant than EDNRB." (PMID 32194414, 2020).
endometrial cancer (2 papers, 1995 to 2023). Primary or metastatic malignant neoplasm involving the endometrium (mucous membrane that lines the endometrial cavity). "In this study, EDRNA was overexpressed, especially in G1 cancer same as EDN1, while EDNRB levels were decreased in endometrial cancer compared to the control." (PMID 36542159, 2023). "In turn, EDNRB expression was decreased, but these changes were significant only in G2 and G3 endometrial cancer." (PMID 36542159, 2023).
Erythema (2 papers, 2009 to 2024). Redness of the skin, caused by hyperemia of the capillaries in the lower layers of the skin. "In this study, we showed that VitB12 acts as an essential extracellular messenger and an inhibitor of EDNRB, which is believed to contribute to the alleviation of symptoms such as erythema, edema, and itching in atopic dermatitis." (PMID 39194754, 2024).
glomerulosclerosis (2 papers, 2019 to 2021). A hardening of the kidney glomerulus caused by scarring of the blood vessels. "The role of ET-1 promotes glomerulosclerosis is mediated by EDNRB; the administration of BQ-788, EDNRB antagonist, showed downregulation of the ET-1-induced calcium transient pathway that leads to podocyte detachment." (PMID 34326888, 2021).
head and neck cancer (2 papers, 2013 to 2016). A primary or metastatic malignant neoplasm affecting the head and neck. "A combination of methylated genes of endothelin receptor type B and homeobox protein A9 in deep surgical margin was linked to poor locoregional recurrence-free survival in head and neck cancer patients." (PMID 27009367, 2016).
lung diseases (2 papers, 2015 to 2021). "There was some evidence that EDNRB, RXFP1, ANGPT1, and TEK are closely related to lung diseases and cancer." (PMID 34039311, 2021).
migraine (2 papers, 2016 to 2022). "Receptors directly associated with migraine or pain include endothelin receptor type B (EDNRB), GIPR, and hypocretin receptor 1 (HCRTR1)." (PMID 35453627, 2022).
sensorineural deafness (2 papers, 2011 to 2012). "In humans, EDNRB mutations are frequently associated with sensorineural deafness in addition to aganglionosis, indicating that the Ednrb gene plays a role in the migration and proliferation of neural crest-derived cochlea melanocytes." (PMID 21915282, 2011). "Even among the few human cases of a 13q deletion (including the entire EDNRB locus) associated with WS4, only one case with the full WS4 phenotype (discoloured irides, HD and sensorineural hearing loss) was reported." (PMID 23300849, 2012).
tongue cancer (2 papers, 2012 to 2020). A malignant neoplasm affecting the tongue. "We performed Ki67 chromogenic staining to determine whether macitentan and EDNRB re-expression had an antiproliferative effect at the cellular level in the tongue cancer mouse model." (PMID 33257729, 2020).
vitiligo (2 papers, 2020 to 2024). Generalized well circumscribed patches of leukoderma that are generally distributed over symmetric body locations and is due to autoimmune destruction of melanocytes. "We found that the gene expression patterns of multiple drugs were significantly correlated with the down-regulated gene expression patterns in vitiligo patients, where rosiglitazone may increase melanogenesis by activating the EDNRB gene." (PMID 38159176, 2024). "Based on this, we proposed the hypothesis that PPAR-γ expression is impaired in vitiligo patients, and rosiglitazone may promote pigmentation through upregulation of PPAR-γ and EDNRB genes." (PMID 38159176, 2024). "Subsequently, the results of immunofluorescence staining showed that the expression levels of PPAR-γ, TYR, and EDNRB were significantly reduced in non-segmental vitiligo patients’ lesions skin along with the number of MITF-labeled melanocytes." (PMID 38159176, 2024). "Moreover, DCT, TYR, EDNRB and TYRP1 have also been reported previously playing a vital role in vitiligo." (PMID 32509450, 2020). "Therefore, other differential genes which were enriched along with WNT6, DCT, TYR, EDNRB and TYRP1 by GO could provide more insights on vitiligo prognosis." (PMID 32509450, 2020). "By direct immunofluorescence, we examined the expression of PPAR-γ and melanogenesis-related genes EDNRB, MITF, and TYR in the skin tissues of non-segmental vitiligo patients (n = 5) and healthy people (n = 5)." (PMID 38159176, 2024). "Consistent with the results of bioinformatics analysis, the expression levels of PPAR-γ, EDNRB, and TYR were significantly reduced in human non-segmental vitiligo skin along with the reduction of MITF, a key gene for epidermal melanogenesis." (PMID 38159176, 2024). "Furthermore, we found that in healthy skin, PPAR-γ and EDNRB were significantly expressed in the nuclei of both keratinocytes and melanocytes, whereas in the epidermis of non-segmental vitiligo patients the expression of PPAR-γ and EDNRB was significantly reduced." (PMID 38159176, 2024).
Airway obstruction (1 paper, 2007). Obstruction of conducting airways of the lung. "In the hospital-based asthmatic population, we found a strong association between the EDNRB-30G>A SNP and the degree of airway obstruction." (PMID 17470272, 2007). "As we analysed the subgroup of asthmatic subjects in this population, we again found a strong association between the EDNRB-30G>A SNP and the degree of airway obstruction." (PMID 17470272, 2007). "Altogether, these data emphasize that EDNRB polymorphism could be a determinant of airway obstruction in patients with predisposing factors." (PMID 17470272, 2007). "The purpose of this study was therefore to investigate whether genetic polymorphisms of preproET-1, EDNRA and EDNRB genes were associated with the degree of airway obstruction assessed by the forced expiratory volume in one second (FEV1)." (PMID 17470272, 2007). "The purpose of this study was to investigate whether the genetic polymorphisms of preproET-1, EDNRA and EDNRB genes were associated with the degree of airway obstruction, assessed by FEV1." (PMID 17470272, 2007). "However, we have no argument to support that this could influence the relationship between the EDNRB gene polymorphism and the degree of airway obstruction assessed by FEV1." (PMID 17470272, 2007). "Differences in lung function measurements and prevalence of airway obstruction according to the EDNRB genotype in the hospital-based population of asthmatic patients." (PMID 17470272, 2007).
Allergy (1 paper, 2019). An allergy is an immune response or reaction to substances that are usually not harmful. "In addition, allergy may induce the activation of spinal microglia and astroglia via the ET1/EDNRB pathway, which might activate second-order sensory neurons and predispose allergic individuals to NeP." (PMID 31920952, 2019).
angiomyolipoma (1 paper, 2018). A neoplasm with perivascular epithelioid cell differentiation often associated with tuberous sclerosis. "We have analyzed the expression of EDN1 and of its receptors EDNRA and EDNRB in primary LAM cells as well as in a TSC2 mutated cell line derived from an angiomyolipoma." (PMID 30279475, 2018).
bowel obstruction (1 paper, 2015). "have recently published a study in which they performed bone marrow transplants from EdnrB-/- animals to Rag2-/- recipients, as well as inducing bowel obstruction in WT animals." (PMID 26061883, 2015). "However, when their study is put in the context of their prior work, in which ~40% of EdnrB-/- animals develop HAEC after surgical relief of obstruction, one can conclude that relieving the bowel obstruction is not sufficient to prevent the development of HAEC." (PMID 26061883, 2015).
breast tumor (1 paper, 2020). "Unlike the data from cultured primary breast cells, normal/uninvolved breast tissue expressed significantly higher EDNRB than the breast tumor samples, suggesting that stromal cells may contribute to the EDNRB expression observed in human tissue samples." (PMID 32201539, 2020).
Duodenal stenosis (1 paper, 2022). The narrowing or partial blockage of a portion of the duodenum. "In summary, we consider that haploinsufficiency of EDNRB might be a candidate gene to produce the phenotype of duodenal stenosis/atresia in a fetus with 13q deletion syndrome." (PMID 35045821, 2022).
dwarfism (1 paper, 2022). "Other regions included novel candidate genes that might contribute to the phenotypic variation among the analyzed breeds, including genes for pigmentation-related traits (EDNRA, EDNRB, MITF and OCA2) and body size, with a strong candidate for dwarfism in rabbit (COL2A1)." (PMID 35062866, 2022).
emphysema (1 paper, 2019). "Furthermore, RNA-seq profiling revealed some significantly associated emphysema genes, including asparaginase-like 1 (ASRGL1), latrophilin 2 (LPHN2), and endothelin receptor type B (EDNRB)." (PMID 31651369, 2019).
HCMV infection (1 paper, 2021). "Previously, we found that HCMV infection upregulates the endothelin receptor type B (ETBR) at the transcriptional and protein levels in endothelial and smooth muscle cells, which raised the possibility that this receptor or the endothelin axis may play an important role during HCMV infection." (PMID 34831300, 2021).
hearing disorder (1 paper, 2022). A disorder characterized by the partial or complete loss of the ability to detect sounds due to damage to the ear structures or inability of the brain to properly interpret or process the auditory signals it receives from the anatomic structures of the ear. "Notably, five GPCRs (V2R, EDNRB, S1PR, VLGR1, and mGluR7) of them in the cochlea have been reported to be directly associated with human hearing disorders." (PMID 36311029, 2022).
hypopharyngeal cancer (1 paper, 2024). Carcinoma, predominantly squamous cell, arising from the epithelial cells of the hypopharynx. "In a previous study, hypermethylation of the promoter region of EDNRB was frequent in primary HNSCC and preferentially methylated in salivary rinses of patients with HNSCC (including 5% of hypopharyngeal cancers)." (PMID 38538728, 2024).
idiopathic pulmonary fibrosis (1 paper, 2025). Idiopathic pulmonary fibrosis (IPF) is a nonneoplastic pulmonary disease that is characterized by the formation of scar tissue within the lungs in the absence of any known cause. "Endothelin receptor antagonists (ERAs) targeting the endothelin B receptor (EDNRB) exhibit multidimensional therapeutic potential, particularly in idiopathic pulmonary fibrosis (IPF)." (PMID 40589973, 2025). "Experimental results show that Bosentan, Sitaxentan, and Ambrisentan inhibit the level of pulmonary fibrosis by upregulating EDNRB." (PMID 40589973, 2025). "In the pathological process of pulmonary fibrosis, EDNRB may influence the proliferation of fibroblasts and their transition into myofibroblasts." (PMID 40589973, 2025). "This study utilized bioinformatics analysis to explore the mechanisms of anoikis-associated genes in Idiopathic Pulmonary Fibrosis (IPF) and their potential molecular targets, focusing on the endothelin B receptor (EDNRB) and the possible use of endothelin receptor antagonists in treating IPF." (PMID 40589973, 2025). "Although specific literature on the role of endothelin receptor type B in pulmonary fibrosis is lacking, our study shows that this receptor is important for apoptosis." (PMID 40589973, 2025).
juvenile open angle glaucoma (1 paper, 2022). Juvenile glaucoma (JG) is a rare autosomal dominant open angle glaucoma, characterized by early onset, severe elevation of intra ocular pressure of rapid progression, leading to optic nerve excavation and, when untreated, substantial visual impairment. "The mutations in EDNRB may explain both ophthalmic features of WS and juvenile open-angle glaucoma in this patient." (PMID 35790984, 2022).
kidney cancer (1 paper, 2020). Primary or metastatic malignant neoplasm involving the kidney. "Interestingly, we observed a non-significant positive association between EDNRB and pAKT in cancer cell lines derived from human kidney cancer, but not liver and ovarian-derived cancer cell lines." (PMID 32201539, 2020).
lymphopenia (1 paper, 2015). Reduction in the number of lymphocytes. "We observed splenic lymphopenia in the EdnrBNCC-/- animals (EdnrBNCC+/- 2.6x107±0.19x107 vs. EdnrBNCC-/- 1.2x107±0.19x107, p = 0.002), as has previously been described in the conventional EdnrB mutants." (PMID 26061883, 2015).
metabolic syndrome (1 paper, 2015). A cluster of metabolic risk factors for CARDIOVASCULAR DISEASES and TYPE 2 DIABETES MELLITUS. "Otherwise we have not found any association between EDNRB polymorphisms and other parameters as metabolic syndrome, HOMA-IR or glucose levels." (PMID 25799405, 2015). "We have analyzed if EDNRB polymorphisms were associated with glucose levels and metabolic syndrome (defined by ATP III and IDF criteria) and we have not found any association of rs5351 and rs3759475 with these parameters." (PMID 25799405, 2015).
metastatic disease (1 paper, 2002). "In a further 33 tumours, reduced endothelin receptor type B expression correlated with death from metastatic disease." (PMID 12439722, 2002). "The results of our analysis are significant because they show EDNRB down-regulation to be statistically related to known predictive factors and, indeed, to metastatic disease." (PMID 12439722, 2002). "We also show that EDNRB expression correlates with known predictive factors for survival and with the incidence of metastatic disease." (PMID 12439722, 2002). "Two patients developed metastatic disease despite having a normal EDNRB level." (PMID 12439722, 2002).